CCR4 (C-C motif chemokine receptor 4)
Diseases named in the same sentence as CCR4 in open-access papers (continued):
Sharing a sentence is not in itself a finding about the gene and the disease.
tumor (continued). "The CCR4 is expressed in approximately 30–65% of PTCL tumor cells, including high expression (~ 65%) in ALK− ALCL, variable expression (30–40%) in PTCL-NOS, AITL, and transformed mycosis fungoides (MF), while rarely expressed in ENKTL or ALK+ ALCL." (PMID 33292562, 2020). "Human tumor-infiltrating Treg cells, which suppress anti-tumor immunity, express high levels of the chemokine receptor CCR4." (PMID 31997007, 2020). "In cHL specifically, TARC is known to be secreted in a high quantity from Reed–Sternberg (RS) cells, which can result in Treg migration to the tumor microenvironment through the CCR4 expression on Tregs." (PMID 33050054, 2020). "What is more, a possible link between tumor immunity and aberrant expression of CCR4 in GC cells has been proved." (PMID 33182840, 2020). "Pathology of the CCR4 IT‐alone group showed sporadic tumor cell areas, demonstrating that CCR4 IT treatment is more effective against the tumor cells than IL2 fusion toxin treatment." (PMID 32107846, 2020). "CCL17 and CCL22 are responsible for CCR4-dependent recruitment of Treg into the tumor niche, which enhances cancer immune evasion." (PMID 33182504, 2020). "Most studies have shown that CCR2/CCR4 are highly expressed in tumors and promote tumor progression." (PMID 33318300, 2020). "CCR4 blockade inhibited tumour growth and Tregs infiltration into tissues with improved survival and a low incidence of clinically relevant toxicity." (PMID 32680511, 2020). "BRAFV600E signalling in melanocytes controlled the expression of CCR4-cognate chemokines and governed the recruitment of Tregs to tumour-induced skin sites." (PMID 32680511, 2020). "This pathology analysis confirms that the IL2 fusion toxin has efficacy in depletion of human CD25+CCR4+ tumor cells." (PMID 32107846, 2020). "In an experimental model of Hodgkin lymphoma, a noteworthy strategy took into account that the lymphoma cells predominantly produce CCL17 and CCL22 and recruit CCR4+ Th2 and Treg cells, resulting in an immunosuppressive tumor microenvironment." (PMID 32620049, 2020). "This approach has been evaluated in a mouse model of cHL, which showed enhanced tumor killing by CD30.CCR4.CAR-T cells as compared to CD30.CAR-T cells." (PMID 33050054, 2020). "This was in support of CCR4 blockade reducing tumor-infiltrating Tregs and enhancing anti-tumor immunity especially when combined with tumor vaccines." (PMID 33375291, 2020). "The human anti-CCR4 antibody Mogamulizumab eliminates tumor cells via antibody-dependent cellular cytotoxicity (ADCC) and is actually in use in Japan for the treatment of relapsed/refractory ATL." (PMID 30894861, 2019). "Further analysis showed that the high expression of Nav1.6 was closely related to the one of CCR2\CCR4 in tumor lymph node metastasis." (PMID 31672162, 2019). "MAIT cells in circulation have been shown to express receptors for IP-10 (CXCR3) and CCL22 (CCR4), respectively, rendering them receptive to these chemokines, however, what this means for anti-tumor immunity is currently unclear." (PMID 31354725, 2019). "In hematological malignancies targeting of overexpressed chemokine receptors directly kill tumor cells but can potentially induce unwanted immune reactions (e.g., CCR4)." (PMID 30894861, 2019). "CCL17 and CCL22 acting on CCR4 can directly recruit Tregs and Th2 lymphocytes, that promote tumor growth and proliferation." (PMID 30894861, 2019). "We observed that Plasmodium infection significantly downregulated the expression of the chemokines CCL17 and CCL22 as well as their receptor, CCR4 in the tumor microenvironment further validating the reduction in the proportion of Tregs in the tumor tissues." (PMID 30979375, 2019). "Monovalent, bivalent and single-chain fold-back diabody anti-human CCR4 DT-based immunotoxins were successfully produced in yeast and demonstrated to be effective and specific in a human CCR4+ tumour bearing NSG mouse model." (PMID 31108917, 2019).
tumor (continued). "Expression of the host CC chemokine receptor CCR4 is observed in 90% of tumor cells isolated from individuals living with ATL." (PMID 31616431, 2019). "It has been reported that CCL22 and CCR4 are also expressed in several types of tumor cells and Foxp3+ Treg, respectively." (PMID 30718772, 2019). "The main chemokines involved in oral carcinogenesis, tumor invasion and metastasis are CCR4, CCR5, CCR7 and CXCR4, and our aim was to evaluate the prognostic value of the immunoexpression of these chemokines in SCC of tongue and floor of the mouth." (PMID 31011147, 2019). "CCR4 was positive in the tumor cells of 9/15 ALK− ALCL cases (60%), 10/15 ALK+ ALCL cases (67%) and 6/10 cHL cases (60%)." (PMID 31581676, 2019). "When the chemokine (CCL22), which is a ligand for CCR4, is produced in tumor tissues, regulatory T cells accumulate in tumor tissues." (PMID 31623180, 2019). "Various forms of DT-antiCCR4 fusions have been investigated, including monovalent DT390-scFv, bivalent DT390-biscFv, and DT390-Fold-back diabody with the aims of directly depleting both human CCR4+ tumor cells and CCR4+ Tregs as a combined cancer treatment." (PMID 31681205, 2019). "In vivo, CCR4 overexpression promoted primary tumor growth and enhanced brain metastases formation in immunocompromised nude mice." (PMID 30420855, 2018). "The in vivo efficacy for targeting human CCR4+ tumors was characterized using the human CCR4+ tumor‐bearing immunodeficient NSG mouse model." (PMID 29873181, 2018). "By immunohistochemistry, we detected CCL17/TARC and its receptor CCR4 in the tumor cells of all MCC tissue samples analyzed." (PMID 30140381, 2018). "Among these is TARC, a chemokine which binds to the chemokine receptor CCR4 expressed on malignant cells, regulatory T cells, and Th2 cells that are enriched in tumor tissue." (PMID 29967610, 2018). "Collectively, these findings suggested that CCR4 promote cancer metastasis and tumor angiogenesis through the up-regulation of MMP2 via ERK/AKT pathways in HCC." (PMID 28959024, 2017). "In ovarian cancer CCR4+Tregs migrate towards CCL22 produced by tumor cells or by the tumor microenvironment, thereby creating favorable conditions for tumor growth." (PMID 28415693, 2017). "Based on the results above, in vivo model was employed to further confirm the enhancing effect of CCR4 on tumor metastasis." (PMID 28959024, 2017). "In these cases, CCR4 positive expression was detected in 47 (62.7%) of the tumor tissues (P = 0.041)." (PMID 28959024, 2017). "In contrast, there was a higher frequency of CD4+ T lymphocytes expressing CCR4 in the tumor tissue." (PMID 29020986, 2017). "And previously by others the interaction between CCR4 expressed by tumor cells and its ligands promotes the proliferation of the tumor cells." (PMID 28415693, 2017). "To elucidate the role of CCR4 in tumor development in vivo, we established orthotropic xenograft tumor models." (PMID 28959024, 2017). "Only the mouse group which received both NK cells and anti-CCR4 antibody therapy showed significant suppression in tumor growth." (PMID 29222435, 2017). "Taken together, these results indicated that CCR4 was capable of manipulating the tumor angiogenesis ability of HCC cells in vitro and in vivo." (PMID 28959024, 2017). "IHC staining of 75-paired tissues indicated that CCR4 expression was significantly higher in HCC tissues than in the non-tumor tissues." (PMID 28959024, 2017). "Based on the results above, Tumor Metastasis PCR array was employed to further pinpoint the key molecular in CCR4 related metastasis." (PMID 28959024, 2017). "Ti-Treg and Ti-Teff cells are the main subsets of CD4+CCR4+ T cells, and they always are recruited into the tumor microenvironment via the CCL2/CCR4 axis." (PMID 29312296, 2017). "The frequency of tumor-infiltrating CD8+ T cells in the CCR4 antagonist-treated group was higher than in the control groups (P < 0.05 for each)." (PMID 27177223, 2016).
tumor (continued). "The frequency of tumor-infiltrating CD4+ T cells was higher in the CCR4 antagonist-treated group than in the control groups, but the difference was not statistically significant." (PMID 27177223, 2016). "The frequency of tumor-infiltrating aTreg cells was also lower in the CCR4 antagonist-treated group than in the PBS/blank control groups (P < 0.05 for each), suggesting that the CCR4 antagonist inhibited aTreg cell migration in vivo." (PMID 27177223, 2016). "Blocking MCP-1/CCR4 signaling-induced aTreg cell recruitment using a CCR4 antagonist evoked antitumor immunity in mice, and lead to inhibition of tumor growth and prolonged survival." (PMID 27177223, 2016). "ADCC is an important tumor cell-killing mechanism of action of mAbs including the anti-CCR4 mAb mogamulizumab, which has been approved for CCR4-positive ATL and relapsed/refractory PTCL in Japan." (PMID 27289375, 2016). "The CC chemokine ligand 22 (CCL22) and the weaker CC chemokine ligand 2 (CCL2) are among the first molecules revealed to attract Tregs to the tumor site by binding to CC chemokine receptor 4 (CCR4)." (PMID 26973839, 2016). "Blockade of chemokine receptor 4 (CCR4) by an antagonist was recently reported to inhibit migration of regulatory T cells to tumors, and thereby enhancing anti-tumor vaccination." (PMID 27076190, 2016). "To investigate the potential molecular mechanism involving CCR4-induced cells invasiveness, we profiled differentially expressed metastasis-related genes with a Tumor Metastasis PCR array.and identified MMP13 as a candidate target." (PMID 27356745, 2016). "In these cases, CCR4 positive expression was detected in 69 (59.5%) of the tumor tissues, whereas only 53 (45.7%) of the adjacent normal specimens showed a positive CCR4 signal (P = 0.035)." (PMID 27356745, 2016). "The affinity between chemokine (C-C motif) ligand 2 (CCL2) released by tumor cells and chemokine (C-C motif) receptor 4 (CCR4) expressed on Treg cells has been shown to play a major role in the recruitment of Treg cells to tumor sites." (PMID 27887569, 2016). "Particularly, transient inhibition of Treg migration by using small molecule antagonists to CCR4 was shown to provide robust antigen-specific CD8+ T cell responses during anti-tumor vaccination." (PMID 27076190, 2016). "A remarkable correlation between expression of CCR4 and tumor size, invasion depth, or lympthatic metastasis was found, indicating that cancer cells with high level of CCR4 have more invasive phenotype." (PMID 27356745, 2016). "Apparently increased CCL22 attracted CCR4-expressing Treg cells to tumor microenvironment in SSCC, compared to NIP." (PMID 26020249, 2015). "Even more, CCL17/TARC and CCL22/MDC produced by both tumor and infiltrating cells in different types of cancer are able to recruit CCR4+ regulatory T and polarized Th2 cells that inhibit anti-tumor responses contributing to tumor survival." (PMID 26062132, 2015). "In patients with ovarian carcinoma, the host response to the tumor has been shown to be inhibited by Foxp3+CCR4+ Tregs recruited to the tumor by CCL17 and CCL22." (PMID 26197455, 2015). "Skin-homing T cells CC-chemokine receptor 4 (CCR4) binds to CCL22 (macrophage-derived chemokine) expressed by tumor-associated macrophages (TAM) and are recruited to the tumor site." (PMID 32309563, 2015). "Tregs express CCR4; abundant expression of CCL22, the ligand for CCR4, in the tumor microenvironment stimulates the tumor infiltration of Tregs." (PMID 26528477, 2015). "The levels of CCL17 (TARC), a ligand for CCR4, positively correlated with the numbers of tumor-infiltrating Th17, Th1 and CD8+ T lymphocytes." (PMID 25949860, 2015). "On the contrary, we did not found increased expression of CCL17 and CCL20, the two specific ligands of CCR4, in tumor tissue." (PMID 25768730, 2015). "The generated anti-CCR4 antibodies possess a dual mode of action (inhibition of ligand-induced signaling and antibody-directed tumor cell killing)." (PMID 25080123, 2014).
tumor (continued). "Implanted orthotopic primary tumors “remotely” stimulate the expression of CCL17 and CCL22 in the lungs, which attract both CCR4(+) Tregs and tumor cells." (PMID 25110692, 2014). "For instance, in a highly metastatic breast cancer model, only a proportion of CCR4(+) tumor cells in the primary tumor establish lung metastasis." (PMID 25110692, 2014). "CCR4/CCL22 even induces Tregs to selectively infiltrate into a particular site in the tumor, such as the area of lymphoid aggregates where Tregs are activated and proliferate in response to tumor-associated antigens presented by DCs." (PMID 25110692, 2014). "In summary, we have generated a set of fully human and affinity matured antibodies against a chemokine receptor CCR4 and showed their anti-tumor activity both in vitro and in an animal model." (PMID 25080123, 2014). "The anti-tumor activity in vivo of human anti-CCR4 antibodies was investigated in a xenograft model bearing murine effector system." (PMID 25080123, 2014). "These antibodies effectively competed with ligand binding, were able to block ligand-induced signaling and cell migration, and demonstrated efficient killing of CCR4-positive tumor cells via ADCC and phagocytosis." (PMID 25080123, 2014). "Although none of these markers is specifically expressed on Tregs and some of them are also present on activated T cells, recent studies demonstrate the efficacy of anti-CTLA-4 or anti-CCR4 to reactivate immune responses against tumours." (PMID 25050936, 2014). "In melanoma, deletion of CD45RA(−)FoxP3(hi)CD4(+) Tregs (effector Tregs) using anti-CCR4 antibody significantly augmented CD8(+) T cell infiltration in the tumor and unmasked a nascent antitumor host response." (PMID 25110692, 2014). "The recruitment of Tregs into the tumor microenvironment depended on the presence of CD8(+) T cells that produce ligands for CCR4." (PMID 25110692, 2014). "Secreted CCL22 binds to the C-C chemokine receptor 4 (CCR4) on circulating Tregs, that migrate into the tumor microenvironment." (PMID 24312199, 2013). "These tumor-infiltrating effector Tregs dominantly expressed CCR4, proposing CCR4 as a possible target for Treg control (manuscript in preparation)." (PMID 23874336, 2013). "In the second treatment study (model 2), AAV8-h1567 gene delivery together with human PBMCs was evaluated and a significant inhibition of CCR4+ Mac-1 tumor cell growth was again seen." (PMID 22973452, 2012). "In vivo studies using therapeutic mAb gene transfer after CCR4+ tumor cell implantation demonstrated the potent antitumor activity of the mAb h1567." (PMID 22973452, 2012). "These tumor migrating CCR4+ CD4+ T cell effector subsets, however, were found at similar levels between patients and controls." (PMID 24213326, 2012). "CCR4 is expressed at high levels on T regulatory cells (Tregs) that can migrate to tumor cells that secrete the CCR4 chemokines CCL17 and CCL21 to facilitate evasion from immune surveillance." (PMID 22973452, 2012). "The therapeutic CTCL model was further extended to evaluate the role of human effector cells in tumor cell killing using bioluminescence imaging (BLI) of luciferase expressing CCR4+ Mac-1 cells established by retroviral transduction." (PMID 22973452, 2012). "High level, durable expression of the h1567 minibody was achieved after a single intravenous injection and significant anti-tumor activity against CCR4+ Mac-1 cells was seen in two animal treatment studies." (PMID 22973452, 2012). "In this study, we used recombinant adeno-associated viral (AAV) vector-mediated antibody gene transfer into SCID-BEIGE mice to evaluate the effectiveness of h1567, a novel humanized anti-CCR4 mAb to inhibit CCR4+ tumor cell growth and increase survival." (PMID 22973452, 2012). "Over the past decade, CCR4 and its ligands have been demonstrated to play critical role in recruiting circulating Tregs into tumor tissue." (PMID 21935436, 2011).
tumor (continued). "Tumor-infiltrating Th17 cells express high levels of CCR4 and CCR6 and therefore respond to tumor-derived CCL20 signals." (PMID 21197451, 2011). "We thus reasoned that these chemokines could directly stimulate the growth of EO771 tumor cells and tested this hypothesis by using a small molecule CCR4 antagonist." (PMID 40036145, 2025). "CCR4 may also contribute to the establishment of immunosuppressive conditions in the tumor microenvironment." (PMID 40896244, 2025). "In our study population, however, all cases expressed CCR4 on more than 10% of tumor cells." (PMID 40833211, 2025). "Moreover, chemokines such as C-C motif chemokine ligand 22 (CCL22) recruit immunosuppressive Tregs to the tumor site via C-C chemokine receptor type 4 (CCR4)." (PMID 40672956, 2025). "This directs Treg that are enriched for the CCL22 receptor, CCR4, to infiltrate the tumor site." (PMID 40894040, 2025). "Moreover, the application of anti‐CCR4 monoclonal antibodies significantly reduces the number of intra‐tumoral Tregs, thereby alleviating Treg‐induced tumour immunosuppression." (PMID 40000397, 2025). "Accumulation of Tregs is driven by the chemokine C-C motif chemokine 22 (CCL22) produced predominantly by the tumor, as well as by tumor-associated macrophages and dendritic cells in the TME via interaction with its counter receptor, chemokine receptor 4 (CCR4), expressed on Tregs." (PMID 41303751, 2025). "CCL17 regulates immune cell infiltration through its receptor CCR4, suppressing tumor progression." (PMID 40517358, 2025). "Furthermore, CCR4 is highly expressed on Tregs, and chemokines secreted by tumor cells can attract CCR4+ Tregs into the tumor niche." (PMID 40703514, 2025). "The results of these experiments confirmed our hypothesis, indicating that blockade of CCR4 significantly reduced tumor cell growth when EO771 cells were co‐cultured with WT BMDMs." (PMID 40036145, 2025). "Moreover, specific ligands for CCR4, produced by the tumour cells and the tumour microenvironment cells, attract CCR4+ Treg cells, leading to tumour immune escape in different types of cancers." (PMID 38804300, 2024). "Additionally, a study using an oral CCR4 antagonist combined with ICB (anti-CTLA-4 or anti-PD-1) therapy in a mouse tumor model demonstrated that the combination therapy is more effective against tumors than monotherapy." (PMID 38500876, 2024). "The significance of CCR4 expression in tumor cells was unclear in the current case." (PMID 38780761, 2024). "Mechanistically, while the mechanism of action of mogamulizumab targeting CCR4 can effectively reduce the malignant T‐cell burden and promote antitumor immunity by depleting Treg cells in the tumor microenvironment, it also leads to hyperactivation of the Th1 immune response." (PMID 39659050, 2024). "In addition to depleting tumor cells, it also effectively engages Tregs expressing CCR4 on their cell surface through ADCC." (PMID 38396877, 2024). "DNMT3A was significantly enriched in the CCL22 and CCR4 promoter regions in tumor tissues." (PMID 39513112, 2024). "CCR4 is expressed by both tumour cells and microenvironment cells." (PMID 38804300, 2024). "Treg cells express CCR4 and are recruited to the tumor microenvironment by CCL22 induction." (PMID 39136031, 2024). "Notably, the interplay between CD73 and CCR4 expression in tumor stroma highlighted a novel cellular entity, CCR4 + CD73 + stromal cells, impacting overall and relapse-free survival." (PMID 38914802, 2024). "CCR4-mediated chemotaxis plays a pivotal role in the progression of various solid tumors, with its primary ligands being produced by T-regulatory cells and macrophages within the tumor microenvironment." (PMID 38254876, 2024). "CCL17 promotes tumor invasion through the CCL17/CCR4/mTORC1 pathway." (PMID 38716256, 2024). "However, there remains limited knowledge about the relationship between CD73, CCL17, and CCR4 within the tumor microenvironment in HCC." (PMID 38914802, 2024).